CFAP119 (cilia and flagella associated protein 119)
Synonyms: C16orf93; CCDC189; MGC104706
Tractability: PROTAC: ubiquitination databases record sites on it.
Gene: Protein-coding gene on chromosome 16 (30,757,423 to 30,762,221, reverse strand). Ensembl gene ENSG00000196118.
Subcellular location: Cell projection, cilium, flagellum; Cytoplasmic vesicle, secretory vesicle, acrosome; Cytoplasm
Subcellular location (Human Protein Atlas): Cytosol; End piece; Mid piece; Principal piece
Gene Ontology:
Cellular component: acrosomal vesicle; cytoplasm; sperm principal piece; axoneme; motile cilium; radial spoke
Genetic constraint (gnomAD): Loss-of-function variants: 38 observed, 41.57 expected, observed/expected ratio (o/e) 0.91, 90% interval 0.7 to 1.2. The upper end of that interval is the gene's LOEUF score, 1.2, which puts it in group 5 of 6, group 1 being the genes least tolerant of losing a copy. Missense variants: 435 observed, 441.86 expected, observed/expected ratio (o/e) 0.98, 90% interval 0.91 to 1.07. Synonymous variants: 178 observed, 180.88 expected, observed/expected ratio (o/e) 0.98, 90% interval 0.87 to 1.11.
Homologues: Orthologues: chimpanzee CFAP119 (99% identical), macaque CFAP119 (95% identical), pig CFAP119 (78% identical), dog CFAP119 (77% identical), mouse Cfap119 (73% identical), guinea pig CFAP119 (73% identical), rat Cfap119 (71% identical), tropical clawed frog cfap119 (32% identical), zebrafish cfap119 (26% identical). Paralogues in human: C8orf74 (17% identical).
Diseases named in the same sentence as CFAP119 in open-access papers:
CFAP119 is named in the same sentence as 3 diseases in open-access papers, as found by Europe PMC text mining. Sharing a sentence is not in itself a finding about the gene and the disease.
CFAP119 shares sentences with these, for which no sentence is quoted: asthenospermia (1 paper); ciliopathies (1); male infertility (1).